LINC01346 (long independently transcribed non-coding RNA 1346)
Gene: Long non-coding RNA gene on chromosome 1 (3,940,486 to 3,955,262, forward strand). Ensembl gene ENSG00000233304.
Diseases named in the same sentence as LINC01346 in open-access papers:
LINC01346 is named in the same sentence as 1 disease in open-access papers, as found by Europe PMC text mining. Sharing a sentence is not in itself a finding about the gene and the disease.
LINC01346 shares sentences with these, for which no sentence is quoted: Alzheimer disease (1 paper).